RREB1 (ras responsive element binding protein 1)
Diseases named in the same sentence as RREB1 in open-access papers (continued):
Sharing a sentence is not in itself a finding about the gene and the disease.
type 2 diabetes (7 papers, 2015 to 2024). "RREB1, initially identified as a repressor of the angiotensinogen gene, is associated with type 2 diabetes in African Americans with end stage kidney disease." (PMID 38812969, 2024). "RREB1 encodes a zinc finger transcription factor that is expressed in several type 2 diabetes-relevant tissues, including pancreatic islets, adipose tissue, liver and skeletal muscle." (PMID 36633628, 2023). "Human donor islets from carriers of type 2 diabetes risk alleles in RREB1 have altered glucose-stimulated insulin secretion ex vivo, consistent with a role for RREB1 in regulating islet cell function." (PMID 36633628, 2023). "In this study, we explore the role of RREB1 in an in vivo zebrafish model, in authentic cellular models of human beta cells and by ex vivo characterisation of human donor islets from carriers of RREB1 type 2 diabetes risk alleles." (PMID 36633628, 2023). "Here, we characterised the role of the type 2 diabetes-associated gene RREB1 in beta cell development and function." (PMID 36633628, 2023). "The shared association between type 2 diabetes risk and quantitative measures of islet function supports the islet as a key tissue mediating disease and suggests a potential role for RREB1 in beta cell development and/or function." (PMID 36633628, 2023). "Genetic fine-mapping identified the coding variant rs9379084 (p.Asp1171Asn) as causal (92% posterior probability for type 2 diabetes), strongly supporting a role for RREB1 as the effector transcript at this locus." (PMID 36633628, 2023). "Taken together, our data are consistent with type 2 diabetes-protective alleles in RREB1 resulting in loss of function." (PMID 36633628, 2023). "There were two common genes between the PD and IR genesets:RREB1, which is a transcription factor, andANKFY1, which is involved in vesicle trafficking and is also implicated in Type 2 diabetes." (PMID 34745571, 2020). "Although genetic genes regulating glycemic trait are not necessarily identical to those leading to the conversion to type 2 diabetes, RREB1 is a risk gene responsible for both fasting glucose and T2D." (PMID 32210733, 2020). "In addition, increasing evidences suggest that RREB1 is a potential risk gene for type 2 diabetes and obesity." (PMID 32210733, 2020). "The big brown bat ATP6V1G3 promoter is predicted to bind RREB1, which represses RAAS through the angiotensin gene and is associated with type 2 diabetes (T2D) end-stage kidney disease." (PMID 38195585, 2024). "A trans-ethnic meta-analysis of type 2 diabetes genome-wide association studies has identified seven novel susceptibility variants in or near TMEM154, SSR1/RREB1, FAF1, POU5F1/TCF19, LPP, ARL15 and ABCB9/MPHOSPH9." (PMID 25799151, 2015). "RREB1 polymorphisms have been shown to interact with APOL1, and are implicated in fat distribution and fasting glucose, a potential explanation for the association with type 2 diabetes." (PMID 38812969, 2024). "Carriers of the minor allele encoding p.Asn1171-RREB1, predicted to have a detrimental effect on Ras-responsive element binding protein 1 (RREB1) function (CADD score 28.2), have a lower risk of developing type 2 diabetes and lower fasting glucose levels, on average." (PMID 36633628, 2023).
Obesity (6 papers, 2018 to 2021). Accumulation of substantial excess body fat. "Overweight-associated dmCpG-hosting genes were significantly enriched in targets for E47, SREBP1, and RREB1 transcription factors, which are known players in obesity and lipid homeostasis, but none overlapped with BMI-dmCpG." (PMID 34025721, 2021).
colorectal cancer (5 papers, 2017 to 2025). A primary or metastatic malignant neoplasm that affects the colon or rectum. "Besides, UBC9 upregulation by RREB1 underlies enhanced SUMOylation and chemoresistance in colorectal cancer." (PMID 41351721, 2025). "RREB1 has been implicated a potential oncogene in colorectal cancer." (PMID 32210733, 2020). "On the other hand, RREB1 inhibition by circITGA7 will increase the expression of ITGA7 to inhibit colorectal cancer growth." (PMID 32210733, 2020). "It represses the expression of RREB1 via Ras pathway to inhibit growth and metastasis of colorectal cancer." (PMID 32210733, 2020). "In pancreatic and colorectal cancer, RREB1 overexpression will promote cancer cell proliferation through the inhibition of tumor suppressor miR-143/145." (PMID 32210733, 2020). "RREB1 has emerged from multiple screens as a likely human oncogene and a driver of colorectal cancer." (PMID 27835861, 2017). "In colorectal cancer, microRNA-143/145 10 and ITGA75 are the target genes regulated by RREB1." (PMID 32210733, 2020).
glioma (4 papers, 2023 to 2026). A benign or malignant brain and spinal cord tumor that arises from glial cells (astrocytes, oligodendrocytes, ependymal cells). "Further, RREB1 can directly regulate NESTIN gene expression which plays an important role as a glioma stem cell biomarker in maintaining glioma stemness." (PMID 36635261, 2023). "Functionally, circNCAPG promotes glioma progression by stabilizing and promoting nuclear translocation of the RREB1 protein, allowing the TGF-β1 signaling pathway to be activated." (PMID 36635261, 2023). "The U2AF65/circNCAPG/RREB1 feedback loop stimulates glioma tumorigenesis by activating the TFG-β1 signaling pathway." (PMID 36635261, 2023). "Finally, we detected the effect of the U2AF65/circNCAPG/RREB1 axis on glioma progression by establishing orthotopic xenograft models." (PMID 36635261, 2023). "However, the biological functions and mechanism of RREB1 in the pathogenesis and progression of gliomas are uncertain." (PMID 36635261, 2023). "In glioma, RREB1 transcriptionally upregulates U2AF65 and improves the stability of circNCAPG." (PMID 37596700, 2023). "Finally, in vivo experiments revealed that the U2AF65/circNCAPG/RREB1 feedback loop also regulates glioma progression in the orthotopic intracranial glioma model." (PMID 36635261, 2023). "Our findings support the existence of a novel feedback loop U2AF65/circNCAPG/RREB1 that promotes malignant progression in GSCs and could be a novel therapeutic target for glioma patients." (PMID 36635261, 2023). "However, the mechanism of RREB1 in promoting tumor progression in glioma is unclear." (PMID 36635261, 2023). "Additionally, a recent study showed that U2AF2 can directly bind and stabilize circNCAPG, which participates in the nuclear translocation of ras responsive element binding protein 1, thereby activating the TGF-β pathway and promoting glioma progression." (PMID 39495216, 2024). "U2AF65 can directly bind and stabilize circNCAPG, circNCAPG participates in the nuclear translocation of RREB1, a transcription factor of unknown function in GSCs, for activating the TGF-β pathway and promoting glioma progression." (PMID 36635261, 2023).
bladder cancer (3 papers, 2013 to 2025). "RREB1 (rs551143, p = 1.84 × 10−10) codes for a zinc-finger transcription factor involved in cell proliferation and DNA damage repair and has been identified previously in GWASs of cutaneous melanoma, bladder cancer, and age-related macular degeneration." (PMID 40495383, 2025).
leukemia (3 papers, 2020 to 2022). A malignant (clonal) hematologic disorder, involving hematopoietic stem cells and characterized by the presence of primitive or atypical myeloid or lymphoid cells in the bone marrow and the blood. "For qPCR validation, these miRNA expression levels (ΔCt) were correlated with HLA-G5 and RREB1 mRNA expressions and sHLA-G bone marrow levels according to the leukemia subtype." (PMID 35774498, 2022). "The top 15 TFs enriched within the K562 cell associated pattern include TAL1, EGR1, RREB1 and NFE2 which have all been associated with leukemia or, in the case of NFE2, is an erythroid nuclear factor." (PMID 32392348, 2020).
cardiac hypertrophy (2 papers, 2020 to 2021). "Mice with one functional copy of Rreb1 exhibit cardiac hypertrophy and sensitization of cardiomyocytes to MAPK signaling." (PMID 34488850, 2021). "Rreb1 hemizygous mice display orbital hypertelorism and cardiac hypertrophy phenocopying the human syndrome." (PMID 32938917, 2020). "Since cardiac hypertrophy and dysfunction are commonly observed in patients with 6p microdeletion and Noonan-like syndromes, the hearts from Rreb1+/− and WT littermates were compared." (PMID 32938917, 2020). "We find Rreb1 hemizygous mice display orbital hypertelorism and age dependent cardiac hypertrophy phenocopying the human 6p25.1p24.3 syndrome." (PMID 32938917, 2020). "Transcripts for the atrial/brain natriuretic factors (ANP, BNP) and β-myosin heavy chain (β-MHC), canonical markers of the fetal gene program and cardiac hypertrophy were up-regulated in Rreb1+/− hearts at 6 months." (PMID 32938917, 2020). "Consistent with cardiac hypertrophy observed in Rreb1+/− mice and sensitization of MAPK signaling in RREB1 haploinsufficient cells, increased p-MEK and p-ERK was observed in left ventricle (LV) from Rreb1+/− hearts compared to WT." (PMID 32938917, 2020).
cardiomyopathy (2 papers, 2020 to 2023). A disease of the heart muscle or myocardium proper. "We provide genetic and biochemical evidence that dysregulation of Fgfr4, Hras and Map2k2 in the heart of Rreb1 heterozygous mice is deleterious leading to a cardiomyopathy that is reminiscent of the phenotype observed in Noonan-like RASopathies." (PMID 32938917, 2020).
chromosome 22q11.2 deletion syndrome (2 papers, 2022 to 2023). "RREB1 is also a candidate factor in the pathogenesis of DiGeorge syndrome, which is associated with craniofacial abnormalities, including cleft palate." (PMID 34897389, 2022). "Responsive element binding protein 1 (RREB1) is a protein-coding gene associated with chromosome 22q11.2 deletion syndrome (22qDS), which may be related to MGCT." (PMID 36805679, 2023). "The expression of RREB1 is dysregulated by an epigenetic mechanism in DiGeorge syndrome." (PMID 34897389, 2022).
colon carcinoma (2 papers, 2018 to 2023). "In colon cancer cell lines, overexpression of these miRNAs down-regulates KRAS, RREB1 and other genes in the MAPK cascade, which abrogate signalling through MAPK, PI3K and JNK pathways." (PMID 29360852, 2018).
gastric cancer (2 papers, 2021 to 2023). A primary or metastatic malignant neoplasm involving the stomach. "KEGG pathway analysis also revealed that the genes upregulated in Rreb1-/- embryos were enriched for pathways associated with cancer, including ‘Pathways in cancer’, ‘MicroRNAs in cancer’, and ‘Gastric cancer’ (3/5 most enriched pathways)." (PMID 33929320, 2021). "Mutations in RREB1 have been observed in pancreatic ductal adenocarcinoma and gastric cancer." (PMID 37596700, 2023).
gestational diabetes (2 papers, 2020 to 2025). Carbohydrate intolerance first diagnosed during pregnancy. "In Japanese populations, the gestational-diabetes-related loci include adiponectin (ADIPOQ), CDKN2A/2B, signal sequence receptor subunit 1-Ras-responsive element binding protein 1 (SSR1-RREB1), and MyoD family inhibitor domain-containing 2 (MDFIC2)." (PMID 40650275, 2025).
gout (2 papers, 2021 to 2025). A condition characterized by painful swelling of the joints, which is caused by deposition of urate crystals. "The polymorphism rs675209 (C > T) in RREB1 was associated with increased SU (Effect size = 0.061, p = 1.3 × 10−23) and increased risk for gout (OR = 1.09, p = 1.1 × 10−2) in individuals of European ancestry." (PMID 33810064, 2021). "Though the exact biological mechanism underlying the association of the forementioned SNPs and the risk of HU or gout is inconclusive, it is presumed that these genetic polymorphisms may reduce the repressor activity functions of RREB1 and INHBC." (PMID 33810064, 2021). "Among the other genes significantly associated with gout, seven loci have also been previously identified in GWAS, including those in the genes SLC17A1, GCKR, SLC22A11, ADH1B, MLXIPL, RREB1 and SLC16A9." (PMID 41075270, 2025).
Intellectual disability (2 papers, 2020 to 2024). "All patients presented with intellectual disability, craniofacial dysmorphisms, and cardiac abnormalities, consistent with Noonan-spectrum disorder, and many of these features, including cardiac defects and craniofacial abnormalities, have also been observed in mice heterozygous for Rreb1 loss." (PMID 38198538, 2024).
Noonan syndrome (2 papers, 2020 to 2023). Noonan Syndrome (NS) is characterized by short stature, typical facial dysmorphism and congenital heart defects. "Rreb1+/− mice were slightly smaller with a wider blunted nose and significantly increased intercanthal distance (ICD, p < 0.001 t-test) compared to WT littermates similar to the changes in the cranial bones observed in the Noonan syndrome mouse model." (PMID 32938917, 2020).
RASopathy (2 papers, 2020 to 2024). Developmental syndromes caused by germline mutations (or in rare cases by somatic mosaicism) in genes that alter the Ras subfamily and mitogen-activated protein kinases that control signal transduction. "Therefore, we propose that RREB1 is a new RASopathy gene that triggers MAPK pathway activation through the loss of epigenetic repressive marks on critical proteins involved in MAPK pathway signaling." (PMID 32938917, 2020). "RREB1 haploinsufficiency thus represents a new category of RASopathy-like syndromes arising through transcriptional overexpression of MAPK pathway genes as a result of deregulated epigenetic control." (PMID 32938917, 2020). "We find that RREB1 haploinsufficiency resembles a RASopathy in both overlap of clinical features and sensitization of RAS-MAPK signaling observed in multiple cell types." (PMID 32938917, 2020). "In distinction to the known RASopathies, which are single gene disorders, the 6p25.1p24.3 microdeletion syndrome arises via transcriptional dysregulation of multiple RREB1 target genes including FGFR4, HRAS and MAP2K2 that result in sensitization of the MAPK pathway to activation." (PMID 32938917, 2020). "However, we postulate that the similarities in phenotypes between available RASopathy mouse models and the Rreb1+/− mice highlight the deleterious effect of overactive RAS-MAPK signaling on organismal development." (PMID 32938917, 2020).
Ataxia (1 paper, 2024). Ataxia refers to impaired coordination of voluntary muscle movement. "A spontaneous mouse mutation causing loss of a nervous system–enriched Rreb1 transcript is associated with progressive loss of cerebellar Purkinje cells and ataxia." (PMID 38198538, 2024).
cleft palate (1 paper, 2022). Cleft palate is a fissure type embryopathy that affects the soft and hard palate to varying degrees. "However, the association of RREB1 with cleft palate has been indicated in some congenital disorders." (PMID 34897389, 2022). "Interestingly, the involvement of RREB1 in cleft palate has been indicated in humans." (PMID 34897389, 2022). "Aberrant RREB1-mediated Ras signaling might be involved in the pathogenesis of cleft palate." (PMID 34897389, 2022).
developmental delay (1 paper, 2020). "Haploinsufficiency of SIN3A and KDM1A mutations lead to similar syndromes characterized by the clinical features observed with RREB1 haploinsufficiency including developmental delay and craniofacial abnormalities." (PMID 32938917, 2020).
Ewing sarcoma (1 paper, 2020). A small round cell tumor that lacks morphologic, immunohistochemical, and electron microscopic evidence of neuroectodermal differentiation. "On the other hand, RREB1-silencing did not produce these co-regulatory effects, demonstrating that in Ewing sarcoma cells, KLF15, TCF4 and NKX2-2 together constitute an inter-connected circuitry." (PMID 33080033, 2020).
glioblastoma (1 paper, 2026). The most malignant astrocytic tumor (WHO grade IV). "Clinical samples further confirmed the co-upregulation of NIBAN2, FLII, and RREB1 in GBM (Glioblastoma) tissues, which correlates with SOX2 and Ki-67 expression and poor prognosis." (PMID 41736673, 2026).
heart failure (1 paper, 2018). Inability of the heart to pump blood at an adequate rate to meet tissue metabolic requirements. "While the role of RREB-1 has not been investigated directly in the heart, these seven transcription factors have well-defined roles in heart failure." (PMID 30241514, 2018).
Hypertelorism (1 paper, 2025). Interpupillary distance more than 2 SD above the mean (alternatively, the appearance of an increased interpupillary distance or widely spaced eyes). "Among them, mice with a deficiency for Fgfr1, Fgfr2, Kif3a, Kras, Ptch1, Rreb1, Sos1, and Tfap2a show excessive proliferation during midfacial development, resulting in hypertelorism, suggesting that mimics of miR-383-3p and miR-6951-3p activate cell proliferation through suppression of these genes." (PMID 40787625, 2025).
intervertebral disc degeneration (1 paper, 2020). "RREB1 has been reported to regulate renin-angiotensin system by inhibiting hANG 27 and to participate in the intervertebral disc degeneration protection by inhibiting the expression of ADAMTS5." (PMID 32210733, 2020).
left ventricular hypertrophy (1 paper, 2020). Enlargement of the LEFT VENTRICLE of the heart. "Rreb1+/− mice developed left ventricular hypertrophy at 6 months of age with pronounced cardiac wall thickening." (PMID 32938917, 2020).
liver fibrosis (1 paper, 2021). "To date, RAS-responsive element binding protein 1 (RREB1) has been identified as a key partner of TGF-β-activated SMAD transcription factors associated with the EMT in liver fibrosis." (PMID 34136500, 2021).
lymphoma (1 paper, 2019). A malignant (clonal) proliferation of B- lymphocytes or T- lymphocytes which involves the lymph nodes, bone marrow and/or extranodal sites.
microcephaly (1 paper, 2021). A congenital or acquired developmental disorder in which the circumference of the head is smaller than normal for the person's age and sex. "At E9.0–9.5, Rreb1-/- embryos showed various defects, including microcephaly (2/7 at E9.5), an open foregut, and an open neural tube at the forebrain, midbrain, and posterior neuropore level (8/10 Rreb1-/- at E9.5)." (PMID 33929320, 2021).
myeloid leukemia (1 paper, 2022). A clonal proliferation of myeloid cells and their precursors in the bone marrow, peripheral blood, and spleen. "It was shown that RAS-responsive element-binding protein 1 (RREB1) was overexpressed in AML patient blasts and myeloid leukemia NB4 and HL-60 cells." (PMID 36291090, 2022).
osteosarcoma (1 paper, 2021). A usually aggressive malignant bone-forming mesenchymal neoplasm, predominantly affecting adolescents and young adults. "The high expression of MELTF-AS1 in osteosarcoma was partly due to the transcriptional activation of RREB1." (PMID 34729248, 2021). "The results of immunohistochemistry (IHC) assays showed that the trend of RREB1 protein level in osteosarcoma tissues was consistent with the RNA level." (PMID 34729248, 2021). "Furthermore, the results of PCR assays revealed RREB1 was significantly elevated in osteosarcoma tissues, and the expression level in osteosarcoma tissues with distal metastasis was higher than that in osteosarcoma tissues without metastasis." (PMID 34729248, 2021). "After silencing RREB1, the expression level of MELTF-AS1 in osteosarcoma cells was significantly reduced, and after overexpression of RREB1, the expression level of MELTF-AS1 increased significantly." (PMID 34729248, 2021).